TMPRSS2 (transmembrane serine protease 2)
Diseases named in the same sentence as TMPRSS2 in open-access papers (continued):
Sharing a sentence is not in itself a finding about the gene and the disease.
COVID-19 (continued). "Similarly, TMPRSS2 facilitates viral entry and is upregulated by androgenic hormones, potentially explaining the higher severity of COVID-19 in men." (PMID 40003732, 2025). "Also, the role of ACE2 and TMPRSS2 in COVID-19 severity will be discussed, considering their significant role in the SARS-CoV-2 pathogenesis." (PMID 39997467, 2025). "Since the start of the COVID-19 pandemic, TMPRSS2 has gained attention as a therapeutic target for protease inhibitors which would inhibit SARS-CoV-2 infection, but little is known about TMPRSS2 regulation, particularly in cell types physiologically relevant for SARS-CoV-2 infection." (PMID 40195420, 2025). "This study aims to determine whether ACE1, ACE2, and TMPRSS2 mRNA expression levels, along with the ACE1 Alu 287 bp polymorphism (rs4646994), contribute to the severity and mortality of COVID-19." (PMID 39850833, 2025). "Genetic variations in TMPRSS2 alter COVID-19 patient's vulnerability and disease intensity." (PMID 40297833, 2025). "Prospective, large-scale studies are warranted to validate our findings and determine whether TMPRSS2 suppression translates into measurable improvements in COVID-19 outcomes." (PMID 41150771, 2025). "Thus, existing knowledge underscores the pivotal role of TMPRSS2 in activating this viral group through proteolysis, highlighting its significance as a focal point for COVID-19-related investigation." (PMID 39858469, 2025). "The purpose of this study was to investigate polymorphic variants of the genes FGB (rs1800790), NOS3 (rs2070744) and TMPRSS2 (rs12329760) in patients with SARS-CoV-2 and to determine their role in the COVID-19 severity course against the background of antiviral therapy." (PMID 40573382, 2025). "Camostat mesylate, initially developed for pancreatitis, and nafamostat have exhibited efficiency in blocking TMPRSS2-mediatedSARS-CoV-2 entry, with continuing clinical trials examining its effectiveness against COVID-19, demonstrating potential antiviral characteristics against the virus." (PMID 40297833, 2025). "Inhibitors of TMPRSS2 have demonstrated potential for preventing viral activation and dissemination, emphasizing the requirement for additional studies to develop efficient antiviral methods toward respiratory tract viruses like COVID-19 and influenza." (PMID 40297833, 2025). "Polymorphisms in other host genes, such as TMPRSS2, DPP4, interferon-lambda-3, tolloid like-1, discoidin domain receptor 1 and HLA-DRB1*08, may also contribute to the susceptibility and severity of COVID-19." (PMID 38846354, 2024). "EOSs and Th2 cytokines can reduce ACE2 and TMPRSS2 mRNA expression and inhibit SARS-CoV-2 variants, which may decrease the risk of ECRS patients for COVID-19 and an uncontrolled inflammatory response." (PMID 38481633, 2024). "We found that P450 aromatase, testosterone, and TMPRSS-2 can be markers of COVID-19 severity." (PMID 39449074, 2024). "In line with the role of TMPRSS2 in SARS-CoV-2 infection, rs2070788 G allele has been repeatedly, although not consistently, associated with severe clinical presentation and increased mortality of several respiratory infectious diseases, including COVID-19." (PMID 39744525, 2024). "Hence, the present study demonstrated that ACE2 and TMPRSS2 behavior varies according to the SARS-CoV-2 genomic variant carrying out the infection, possibly influencing the complexity of COVID-19." (PMID 39597701, 2024). "Following the binding of SARS-CoV-2, the causative agent of COVID-19, via its spike protein to the cell surface receptor ACE2 (angiotensin converting enzyme 2), both furin and TMPRSS2 sequentially cleave the spike protein at the S1/S2 and S2’ sites, respectively." (PMID 38339082, 2024). "Moreover, our study demonstrated that COVID-19 patients (76%) had a greater prevalence of the CC genotype of the TMPRSS2 p.Val197Met variation than did the control group (66%) and was also higher in all patient groups compared to CT and TT." (PMID 38254046, 2024).
COVID-19 (continued). "First, SARS-CoV2 binds to a serine protease, which acts as a receptor for the ectoenzyme angiotensin-converting enzyme 2 (ACE2), whereas another transmembrane serine protease 2 (TMPRSS2) is necessary for priming the viral spike protein required to enter the cell, leading to COVID-19." (PMID 38765079, 2024). "Therefore, TMPRSS2 inhibitors have emerged as a promising therapeutic approach for COVID-19, and numerous studies are currently investigating their efficacy." (PMID 38892254, 2024). "The mechanism by which SARS-CoV-2 enters the host cell via interactions with the ACE2 receptor and TMPRSS2 may also be a key explanatory factor for sex-related differences in the lethality of COVID-19." (PMID 38534740, 2024). "Previous studies have predicted that AZ may exhibit anti-COVID-19 activity by regulating estrogen production and following p65-transmembrane serine protease 2 (TMPRSS2) signaling." (PMID 38247540, 2024). "Conversely, a case-control study conducted in Germany, which examined 239 patients diagnosed with COVID-19, did not identify any association between the TMPRSS2 rs2070788 polymorphism and the severity of the disease." (PMID 39188881, 2024). "Hence, this study strived to establish a relationship between ACE2 and TMPRSS2 expression profiles and genomic variations with SARS-CoV-2 variants to elucidate their possible influence on the complexity of COVID-19." (PMID 39597701, 2024). "Black people have an increased burden of COVID-19, and this may be related to the increased nasal expression of TMPRSS2." (PMID 38263160, 2024). "Since both proteins are essential for the viral cycle of SARS-CoV-2, during the last few years, they have served as protagonists in research studies aiming to comprehend the relationship between expression levels and the genomic sequences of ACE2 and TMPRSS2 and COVID-19." (PMID 39597701, 2024). "While the results of the TMPRSS2 rs12329760 polymorphism showed that the minor T allele and CT and TT genotypes are protective against COVID-19 severity." (PMID 38263160, 2024). "Controlling for other factors of influence, such as CCI, N/L ratio, LDH level, and pO2, we showed that females with TMPRSS2 rs2070788 A/A genotype were less likely to develop severe COVID-19 (odds ratio [OR] [95% confidence interval (95% CI)]: 0.030 [0.001; 0.862])." (PMID 39744525, 2024). "Additionally, in patients previously hospitalized with COVID-19, ACE2 susceptibility and TMPRSS2 polymorphisms were found to be associated with disease severity and the occurrence of long COVID symptoms." (PMID 38638307, 2024). "MM3122 is additionally an excellent TMPRSS2 inhibitor and hence could be a promising candidate against COVID-19." (PMID 38212428, 2024). "On the contrary, ACE2 and TMPRSS2 gene expressions are upregulated by Th1 cytokines such as interferon-γ and tumor necrosis factor α (TNF-α), increasing the susceptibilities of nECRS patients to COVID-19 and further inflammation in OM and OD." (PMID 38481633, 2024). "Additionally, rs2227692 SERPINE1 could participate in hypercoagulable conditions in critical COVID-19 patients, and this genetic variant could contribute to the identification of new pharmacological targets and treatment strategies to block the inhibition of TMPRSS2 entry into SARS-CoV-2." (PMID 38601158, 2024). "In particular, the SNPs in the host apolipoprotein E (ApoE), angiotensin converting enzyme 1 (ACE1), transmembrane serine protease 2 (TMPRSS2), C-C chemokine receptor type 5 (CCR5) and human leukocyte antigen (HLA) loci have been linked to the susceptibility and/or severity of COVID-19." (PMID 38291512, 2024). "TMPRSS2 is a testosterone-regulated gene, the greater expression of which in males may explain more severe COVID-19 outcomes." (PMID 38534740, 2024).
COVID-19 (continued). "Since higher TMPRSS2 levels seemed to be a possible determinant for COVID-19 symptoms in the present study, the usage of protease blockers would show itself to be appealing, although not knowing TMPRSS2 ́s role in human physiology could be a risk." (PMID 38606293, 2024). "Associations of TMPRSS2 and SERPINE1 polymorphisms with COVID-19 severity." (PMID 38601158, 2024). "Both, ACE2 and TMPRSS2, have gained considerable importance and interest on their relevance in the pathogenicity of COVID-19, but these studies utilized samples from patients who were already infected with SARS-CoV-2 and did not have a reference sample from the same patient at another time." (PMID 38606293, 2024). "Our study demonstrates that testosterone, aromatase, and TMPRSS2 are markers of COVID-19 severity." (PMID 39449074, 2024). "It has been postulated from a combination of evidence that a sudden increase in COVID-19 cases among pediatric patients after onset of the Omicron wave was attributed to a reduced requirement for TMPRSS2-mediated entry in pediatric airways with lower expression levels of TMPRSS2." (PMID 38870131, 2024). "TMPRSS2 (2.5 ± 0.31 vs. 1.73 ± 0.21 ng/mL, p < 0.01) and testosterone (1.2 ± 0.1 vs. 0.44 ± 0.12 ng/mL, p < 0.01) were significantly higher in men as compared to women with COVID-19 after adjusting for age in a multivariate model." (PMID 39449074, 2024). "The aim of this study was to determine the associations of the polymorphisms rs2070788, rs75603675 and rs12329760 of the TMPRSS2 gene and the polymorphisms rs2227631, rs2227667, rs2070682 and rs2227692 of the SERPINE1 gene with COVID-19 severity and their relationships with inflammatory biomarkers." (PMID 38601158, 2024). "Impaired ENaC transport in airways of patients with COVID-19 may be thus explained by this dual function of Tmprss2." (PMID 38171596, 2024). "The frequencies of different genotypes/alleles of TMPRSS2 rs2070788 were not correlated with the severity and mortality of COVID-19 compared to different groups." (PMID 39188881, 2024). "In addition, Schwarz and collaborators reported through a proteome wide analysis an antibody response signature in patients with the mild form of COVID-19 that involves two peptides containing the Furin and TMPRSS2 cleavage motifs." (PMID 38628551, 2024). "By presenting evidence, we support the notion that SWTI has the potential to inhibit SARS-CoV-2 infection by targeting the ACE2 and TMPRSS2 pathways, suggesting that it could be a promising nutraceutical for the development of COVID-19 therapies." (PMID 38892254, 2024). "Polymorphisms of TMPRSS2 and SERPINE1 could be associated with COVID-19 severity, modifying the susceptibility to fatal outcomes." (PMID 38601158, 2024). "COVID-19 is caused by the SARS-CoV-2, which requires ACE2 and TMPRSS2 for entry into host cells." (PMID 37893162, 2023). "Moreover, in prostate cancer cells it has been described an effect of androgens on AR (androgen receptor) increasing TMPRSS2 expression, suggesting the correlation of increased lung infections (and severe COVID-19) in men." (PMID 37287057, 2023). "Androgens may be associated with an increased risk of COVID-19 due to their modulatory effects on angiotensin-converting enzyme 2 (ACE2) and transmembrane serine protease 2 (TMPRSS2), the two key factors associated with the entrance of SARS-CoV-2." (PMID 36836216, 2023). "Thus, TMPRSS2 is an ideal pharmacological target for COVID-19 therapy development, and the effective production of high–quality TMPRSS2 protein is essential for basic and pharmacological research." (PMID 37445653, 2023). "In addition to inhibiting ACE2, other characteristics of a potential anti-COVID-19 agent is the ability to inhibit ACE2′s co-receptor known as TMPRSS2, which has the role of facilitating viral entry into host cells." (PMID 38132859, 2023).
COVID-19 (continued). "IVIG may contribute to therapy for COVID-19, including for cases caused by SARS-CoV-2 variants, since IVIG binds not only to the spike proteins of the virus, but also to human ACE2/TMPRSS2." (PMID 36838436, 2023). "The presence of ACE2 and TMPRSS2 in the oral cavity might amplify COVID-19 pathogenesis or worsen periodontitis." (PMID 37893162, 2023). "A recent network analysis revealed that TMPRSS2—which is also located on chromosome 21 and is subsequently overexpressed in Down syndrome—may contribute to COVID-19 severity by promoting increased viral entry." (PMID 37310920, 2023). "Moreover, it has been proved that five single nucleotide polymorphisms (SNPs) within TMPRSS2 and near MX1 gene show associations with severe COVID-19." (PMID 37287057, 2023). "Roxadustat may be beneficial to COVID-19 patients as it can reduce the level of angiotensin-converting enzyme-2 (ACE2) and transmembrane protease serine 2 (TMPRSS2), which is associated with the entrance and replication of SARS-CoV-2 in lung epithelial cells." (PMID 36724056, 2023). "In addition, we showed that SNPs within ACE2, TMPRSS2, NRP1 and CD147 have variable associations with COVID-19 severity across these ethnic groups." (PMID 37761938, 2023). "Our data suggest that IVIG may contribute to therapy for COVID-19, including for cases caused by SARS-CoV-2 variants, since IVIG binds not only to the spike proteins of the virus, but also to human ACE2/TMPRSS2." (PMID 36838436, 2023). "The frequent renal involvement with organ damage in patients with COVID-19 is undoubtedly multifactorial, but the expression on renal cells of the key receptors promoting SARS-CoV-2 entry, such as ACE2, TMPRSS2, and NRP1 can make the kidney particularly susceptible to SARS-CoV-2 infection." (PMID 38255667, 2023). "Since sex and age are important factors influencing the severity of COVID-19 course, the protein levels of ACE2 and TMPRSS2 in membrane fractions obtained from non-COVID-19 human kidneys and colon samples were examined and analyzed as a function of sex and age." (PMID 36979408, 2023). "Initially, it was thought that differences in expression levels or in the genetic variation of the virus entry proteins ACE2 and TMPRSS2 may be host factors that contribute to population differences in COVID-19-induced olfactory dysfunction." (PMID 36766771, 2023). "In addition, ginsenosides will play a role in the prevention and treatment of COVID-19 as an inhibitor of TMPRSS2." (PMID 36992839, 2023). "The increased expression of TMPRSS2 with age (the serin protease responsible for priming the SARS-CoV-2 spike protein of pre-omicron variants) has also been linked to the greater susceptibility of adults to severe COVID-19." (PMID 36680215, 2023). "Therefore, ACE-2 and TMPRSS2 are potential drug targets for treating COVID-19, and their inhibition is a promising strategy for treatment and prevention." (PMID 37809955, 2023). "In addition, we found that ginsenosides, as the inhibitors of TMPRSS2, play different roles in lung cancer and COVID-19 patients, providing new insights into the prevention and treatment of COVID-19 in lung cancer patients." (PMID 36992839, 2023). "Modulating these miRNAs could serve as therapeutic candidates to manipulate ACE2 and TMPRSS2 levels, thereby promoting treatment strategies for severe COVID-19." (PMID 38444707, 2023). "Regarding TMPRSS2, testosterone induces the expression of this receptor for SARS-CoV-2, suggesting that this might be one of the causes leading to higher severity of COVID-19 cases in men than in women." (PMID 38088954, 2023). "TMPRSS2 is a potential target for the treatment of COVID-19 due to its involvement in viral spike protein processing and localization in human epithelial tissues of the respiratory, genitourinary, and gastrointestinal tracts and its coexpression with the coronavirus receptor hACE2 in lung tissues." (PMID 37009799, 2023).
COVID-19 (continued). "Men are more sensitive to COVID-19 because testosterone expression increases TMPRSS2 expression." (PMID 37371774, 2023). "In addition, studies have shown that patients with cancer are at greater risk of being infected by SARS-CoV-2, considering the functions of TMPRSS2 in the COVID-19 infection, medicating the cancer patients infected COVID-19 requires thoughtful consideration." (PMID 36992839, 2023). "Furthermore, other genes such as TMPRSS2 and ACE1 were associated with the mortality of COVID-19 patients (OR = 6.468, 95% CI 1.463–28.592, p = 0.014)." (PMID 38003785, 2023). "Undoubtedly, polymorphisms that alter the ACE2 and spike protein interaction, the TMPRSS2 proteolytic cleavage site, and ACE2 expression correlate with the susceptibility and severity of COVID-19 with some ACE2 variants incurring up to a three-fold increase in the development of severe disease." (PMID 36899952, 2023). "Findings from basic research indicate that androgens may contribute to the progression of COVID-19 by modifying androgen-mediated immune control and upregulating the expression of TMPRSS2, a cellular co-receptor required for SARS-CoV-2 infection." (PMID 37745707, 2023). "TMPRSS2 and ACE2 gene products are necessary for viral invasion of the host cells, which is why their variants are heavily researched and expected to be associated with COVID-19 severity, as well as susceptibility." (PMID 37795240, 2023). "Moreover, many efforts are focused on the role of ACE2 and TMPRSS2 as key markers for COVID-19 severity." (PMID 37287057, 2023). "On the other hand, it has been shown that TMPRSS2-mediated ACE2 cleavage is even more harmful to the host and that an increased expression of TMPRSS2—due to genetics, age or comorbidities—could exacerbate the course of COVID-19." (PMID 37627504, 2023). "The rs2236757 variant interacts with TMPRSS2 and ACE1, influencing COVID-19 severity and mortality." (PMID 38003785, 2023). "Inhibition of TMPRSS2 is a promising avenue for treating COVID-19." (PMID 36724184, 2023). "In addition, SLC6A20 expressionwas positively correlated with COVID-19-associated genes, ACE2, TMPRSS2,and TMPRSS4, in a number of tumor samples." (PMID 37041751, 2023). "In an inhibitory feedback loop, TMPRSS2 reduces ENaC activity, whereas, in the case of COVID-19, the involvement of TMPRSS2 in the invasion process by cleaving the S2’ site of the viral spike protein may attenuate its inhibitory effect on ENaC." (PMID 37189326, 2023). "However, its adverse impacts on COVID-19 patients are attributed to an increase in TMPRSS2, the primary enzyme to cleave and activate the S protein of SARS-CoV-2 in acute SARS-CoV-2." (PMID 36124445, 2023). "ACE2 and TMPRSS2 co-expression in SARS-CoV-2 target tissues may elucidate men’s higher COVID-19 rates." (PMID 37371774, 2023). "As can be seen, TMPRSS2 is a gene that plays a pivotal role in COVID-19 development." (PMID 37287057, 2023). "Thus, in the case of both PRAD and COVID-19, TMPRSS2 and CXCL10 can be considered as two prominent biomarkers." (PMID 36239108, 2022). "Firstly, we did not perform a meta-analysis, utilizing forest plots, given the expected heterogeneity of the study design, analytic model (which includes both COVID-19 patients and healthy subjects from the general population), and measurements of ACE2 or TMPRSS2 gene polymorphisms or mutations." (PMID 35193695, 2022). "Thus, it is recommended to use TMPRSS2 inhibitors in the early stage of COVID-19 or to use them in combination with other anti-viral drugs." (PMID 36464706, 2022). "In addition to trophoblast cells, we also compared ACE2 and TMPRSS2 levels in fetal and maternal endothelial cell types PMVECs from placental specimens and HEECs, respectively to explain COVID-19 severity in pregnancy." (PMID 35464466, 2022).